INS (insulin)
Diseases named in the same sentence as INS in open-access papers (continued):
Sharing a sentence is not in itself a finding about the gene and the disease.
Stroke (continued). "Understanding how insulin affects central neurons could help us better understand how insulin influences stroke prognosis in addition to its many peripheral and metabolic effects." (PMID 38034217, 2023). "Importantly, we also showed that a diet supplemented with high sucrose content in the drinking water impaired insulin sensitivity, providing potentially important clinical implications for the detrimental role of high sucrose on stroke recovery." (PMID 36835405, 2023). "For example, stroke survivors with hemiplegia may have reduced ability to self-administer insulin, cognitive demands of multiple medications may be high, and ability to participate in physical activity may be reduced." (PMID 36721206, 2023). "However, there was no causal association between other antidiabetic drugs (including insulin/insulin analogues, GLP-1 analogues, thiazolidinediones and metformin) and stroke risk." (PMID 37777789, 2023). "Impairments of insulin action on the vessels are major contributors to macro- and microvascular diseases and may likely affect negatively post-stroke recovery." (PMID 36835405, 2023). "Furthermore, insulin and insulin-like growth factor-I (IGF-I) are altered in ischemic stroke (henceforth stroke), and these alterations are associated with recovery after stroke." (PMID 37298072, 2023). "In addition, they also had higher prevalence of DM, HT, previous MI, previous PCI, previous stroke, nitrate at admission and insulin before hospitalization." (PMID 35313877, 2022). "Previous studies showed that peroxisome proliferator-activated receptor (PPAR)-γ, insulin sensitizers, reduced recurrent stroke to 66% (95% CI = 44–99%) in patients with stroke or transient ischemic attack compared to the placebo in a meta-analysis of three randomized clinical trials (RCT)." (PMID 35052672, 2022). "It is also worth noting that recent studies demonstrated that pioglitazone reduced the risk of stroke and myocardial infarction in non-diabetic, insulin-resistant patients with a history of stroke or transient ischemic attack." (PMID 35176115, 2022). "Insulin administration in stroke patients has shifted from intravenous to intranasal." (PMID 36589857, 2022). "The confounding variables were stroke, insulin, calcium channel blocker (CCB), age, and eGFR." (PMID 35690600, 2022). "In multivariable Cox analysis of the parsimonious model, the identified variables were age, male sex, prior stroke, prior MI, chronic kidney disease (eGFR < 60), heart failure, atrial flutter or fibrillation, insulin use, and microvascular diabetic complications." (PMID 36030198, 2022). "Baseline characteristics of excluded patients because of missing insulin data or being treated with insulin are comparable with those who went into final analysis generally, except for the previous stroke/TIA occurrence, smoking status, and admission fasting glucose." (PMID 34394128, 2021). "Although we hypothesized that the stroke group would be more insulin resistant by the glucose clamp, the lower M and 15% lower nonoxidative metabolism in the stroke group was not significantly different than controls." (PMID 33375333, 2020). "Insulin and cortisol levels may be predictors in motor function recovery of stroke patients in rehabilitation process." (PMID 33346224, 2020). "Our findings indicate that in stroke survivors, insulin activation of glycogen synthase is reduced in the paretic compared to nonparetic muscle and that whole-body insulin resistance was related to reduced fitness, visceral and intramuscular fat, and reduced insulin activation of GS." (PMID 33375333, 2020). "Given our earlier findings of paretic skeletal muscle inflammation and increased IMAT in paretic muscle, it is compelling to suggest insulin sensitivity is negatively influenced by inflammation in stroke survivors through these pathways but that remains to be explored." (PMID 33375333, 2020).
Stroke (continued). "However, cases had higher numbers of COPD exacerbations with ER visits, presence of stroke, heart failure, and pneumonia, as well as receipt with co-medications, such as short-acting insulin, diuretics, antiarrhythmic agents, and systemic corticosteroids." (PMID 33267895, 2020). "Insulin-stimulated GS fractional activity was 2.5-fold higher in the control samples, and the absolute changes in GS fractional activity was 2-fold higher in the control samples versus stroke muscle samples." (PMID 33375333, 2020). "In our study, the association between weight changes and stroke and mortality did not change after adjustment for insulin use." (PMID 30890169, 2019). "Akt has been identified as a potential target for stroke therapy through possible modulation of insulin and phosphoinositide 3-kinases (PI 3-kinases), which may stabilize normo-metabolism and ROS recovery processes." (PMID 31847503, 2019). "For nonfatal stroke, the DPP4i-based group but not the insulin-based group had a lower risk than the combined therapy group (HR 0.71, 95% CI 0.64–0.78; HR 0.97, 95% CI 0.85–1.10, respectively)." (PMID 30349614, 2018). "Although studies in patients clearly indicate impaired insulin signaling in both AD and stroke, there has been little investigation of insulin or IGF signaling as a consequence of striatal ischemia and Aβ toxicity, as well as the etiologic link between ischemia and AD." (PMID 29572520, 2018). "One large clinical trial found that treatment with insulin in patients with myocardial infarction was associated with an enhanced risk of recurrent nonfatal myocardial infarction or stroke, while treatment with metformin was more beneficial." (PMID 26382578, 2015). "Among 447 (1.1%) patients with a history of stroke, 351 (79%) belonged to the insulin group." (PMID 25616979, 2015). "During a median 3.5 years of follow-up, cardiovascular event rates per 1000 person-years were significantly lower for the EBID and EBID + insulin groups compared to the insulin group (HF: 4.4 and 6.1 vs. 17.9; MI: 1.1 and 1.2 vs. 2.5; stroke: 2.4 and 1.8 vs. 6.1)." (PMID 25616979, 2015). "Although intensive plasma glucose control with sulfonylureas or insulin does not reduce macrovascular disease, pioglitazone reduces the composite of all-cause mortality, non-fatal myocardial infarction, and stroke in patients with DM." (PMID 24410834, 2014). "In other critically ill (non-stroke) patients with hyperglycemia, initial studies suggested that intensive insulin therapy could be beneficial." (PMID 24777546, 2014). "In the GIST-UK study, patients presenting within 24 h of stroke onset randomized to variable-dose glucose–potassium–insulin had significantly reduced plasma glucose concentration and systolic blood pressure but no significant reduction in mortality at 90 days compared with the control group." (PMID 24777546, 2014). "While insulin injections allow affected individuals to control their blood sugar and stay alive, it is not a cure nor does it prevent the devastating complications of this disease, which include kidney failure, blindness, amputations, heart attack, and stroke." (PMID 12805764, 2001). "A meta‐analysis found no overall association between adiponectin and incident stroke, though subgroup analyses suggest that in insulin‐resistant states, low adiponectin may promote stroke via dyslipidemia and inflammation." (PMID 41567175, 2026). "Therefore, it is essential to control for potential confounding variables, such as insulin use, physical functioning scores, smoking status, and age at first stroke, in order to accurately assess the impact of physical activity on participants’ depressive symptoms." (PMID 39780468, 2025). "However, the study also underscores the importance of considering potential confounding variables such as insulin use, physical functioning scores, smoking status, and age at first stroke to accurately assess the impact of physical activity on depressive symptoms in this population." (PMID 39780468, 2025).
Stroke (continued). "Insulin use was a residual risk factor of CHD but not stroke in this study." (PMID 38263010, 2024). "Based on the findings of this study, insulin may possibly increase risk of CHD but not stroke in statin-treated patients with T2DM." (PMID 38263010, 2024). "However, in our study, the favorable association between WC and post-stroke functional outcomes was not altered by fasting insulin levels, pancreatic β-cell function, or insulin sensitivity." (PMID 38206990, 2024). "Metformin monotherapy may reduce stroke risk, while DPP-4i, SGLT-2i, and insulin do not seem to affect the incidence of stroke." (PMID 39407846, 2024). "Male individuals, those with BCs of Yin deficiency and phlegm stasis, no exercise habits, insulin use, albuminuria, diabetic retinopathy, and cerebrovascular accident were found to have a lower probability of survival compared to individuals who did not have these characteristics." (PMID 38249989, 2023). "Thus, impaired insulin production following peripheral IR could directly affect all these functions, thereby impairing stroke recovery." (PMID 36835405, 2023). "An impaired response to insulin from other brain cells could also affect stroke recovery." (PMID 36835405, 2023). "Data from the ORIGIN trial were used to assess the relationship between three risk factors (weight, systolic blood pressure, and serum insulin) and the hazard of a major cardiovascular event comprising a nonfatal myocardial infarction, nonfatal stroke, or cardiovascular death." (PMID 36479937, 2022). "Although the mechanism underlying the association between the TyG index and stroke recurrence has not been clarified clearly, which may be related to insulin resistance." (PMID 35260102, 2022). "The major identifiable causes of death of the insulin cohort included: 10 (0.97%) CV death (1 ischemic heart disease, 3 sudden cardiac deaths, 1 heart failure, 2 stroke, 3 CV hemorrhage); 142 (13.832%) noncardiovascular death (52 cancers, 90 others); and 14 (1.36%) undetermined cases." (PMID 33655987, 2021). "However, the present analysis showed that a higher risk for death or stroke is not confined only to insulin-treated diabetic patients, but concerns the entire diabetic population, regardless of their treatment." (PMID 33573666, 2021). "Future studies could also be directed at interventions such as exercise training to improve insulin sensitivity in stroke survivors as well as include an in-depth examination of the mechanisms in paretic and nonparetic skeletal muscle in this disabled population." (PMID 33375333, 2020). "Therefore, we may have found a relationship between motor function recovery and insulin and cortisol levels in stroke patients." (PMID 33346224, 2020). "A study on 1,017 non–insulin-independent DM patients with a 7-year follow-up for each patient demonstrated that a high UA level was considerably related to fatal and non-fatal stroke, thus proving the significant association between UA and stroke among T2DM patients." (PMID 32982965, 2020). "We hypothesized that stroke survivors will be insulin resistant by the glucose-clamp technique and have lower insulin-activation of GS compared to controls, and that insulin activation of GS will be more impaired in paretic compared to nonparetic skeletal muscle." (PMID 33375333, 2020). "Neither the hyperinsulinemic-euglycemic clamp technique, the gold standard in the determination of insulin sensitivity, and the measurement of glycogen synthase (GS) activity, a known benchmark index of insulin action in skeletal muscle, have ever been collectively determined in stroke survivors." (PMID 33375333, 2020). "Among patients in the PREvention oF thromboembolic events—European Registry in Atrial Fibrillation (PREFER in AF) registry, insulin users, but not diabetic patients treated with non-insulin antihyperglycemic drugs, were shown to have a higher risk of stroke compared with non-diabetic individuals." (PMID 31540142, 2019).
Stroke (continued). "In regard to safety, long-term studies on transgender men have shown that even higher (male) doses of T do not increase the risk of cardiovascular events, stroke, or cancer; T therapy also increases insulin sensitivity, as opposed to estrogen therapy in transgender women." (PMID 31888528, 2019). "Moreover, we performed the fourth model wherein cardiovascular diseases and medication history (MI, stroke, alcohol use, antihypertensive medication, insulin or oral hypoglycemic agent, lipid-lower therapy, and estrogen replacement) were taken into consideration." (PMID 27645134, 2016). "Therefore, increased expression and/or activity of endothelial NOS or DDAH using selective NCEs is a novel strategy to develop effective insulin sensitizers that are also expected to protect the vascular wall and reduce major adverse cardiovascular events including stroke and heart attack." (PMID 26770984, 2016). "But the data did not really support this hypothesis since the median delay between stroke and treatment was 174 minutes and 86% of the patients in the intensive insulin regimen had a glycemic value under the target (<7 mmol/l) four hours after treatment initiation." (PMID 25793765, 2015). "The pooled HR for CVD, stroke, and CHD across different eGDR categories and continuous eGDR further strengthen the notion that better insulin sensitivity, as indicated by higher eGDR, is protective against CVD events." (PMID 41458544, 2025). "The 10-year risks of fatal stroke in OAD, insulin and OAD plus insulin groups were 0.3%, 0.4%, and 0.4%, respectively." (PMID 38263010, 2024). "A logistic regression was performed to ascertain the effect of insulin (fasting and postprandial), age, FBS, PPBS, HbA1c total cholesterol, TGL, HDL, LDL, VLDL, sex and IHD on the likelihood that participants had a stroke." (PMID 39347227, 2024). "Analysis of a multitude of additional, randomized controlled trials has also revealed an increased stroke incidence compared with metformin, DPP-4 inhibitors, GLP-1 receptor agonists, glitazones or with just insulin." (PMID 38983558, 2022). "In the gastrocnemius muscles of rats with stroke, R-7050 improved activated TNFRI/NF-κB, oxidative stress, and IL-6 pathways, as well as impaired insulin signaling." (PMID 34073455, 2021). "Patients were excluded if aged < 20 years, had a history of stroke or acute coronary syndrome (ACS), or were receiving insulin treatment." (PMID 29368615, 2018). "In our model, CR rats had significantly increased serum IGF1 levels in the first week after stroke that coincided with an accelerated recovery of body weight; IGF‐1 level was further maintained at day 14 by an increase in serum insulin levels." (PMID 28961383, 2017). "Unlike biochemical measures of insulin sensitivity and resistance (non-significant), in age- and sex-adjusted Cox models, MetS was associated with hazard ratio (95% CI) of 2.63 (1.03–6.73) and 3.54 (1.00–12.56) respectively for all-cause and cardiovascular mortality 5 years after stroke onset." (PMID 23565192, 2013). "Both type 1 (insulin-dependent) and type 2 (no insulin-dependent) diabetic patients, have mostly been described under enhanced oxidative stress, and both conditions are known to be powerful and independent risk factors for coronary heart disease, stroke, and peripheral arterial disease." (PMID 16504104, 2006). "Functionally, insulin treatment lowered HOMA2-IR in T2D mice but did not restore cerebral artery myogenic tone or improve stroke outcomes after distal middle cerebral artery occlusion (dMCAO)." (PMID 41827891, 2026). "Regardless of substrate infusion, CRT acutely improved stroke work without increasing O2 uptake on both insulin/glucose (by 34%, P = .05) and intralipid (by 36%, P = .03)." (PMID 39998427, 2025). "For example, consider a 60-year-old married patient with congestive heart failure, coronary artery disease, and stroke and a blood creatinine level of 200 μmol/L who is not taking insulin." (PMID 40060382, 2025).
Stroke (continued). "The box plot represents the distribution of postprandial insulin levels in patients, comparing those with and without a history of stroke." (PMID 39347227, 2024). "Patients who used both insulin and OAD (4.3%, 95% CI 3.2 ~ 5.5%) had higher 10-year risk of nonfatal stroke (P = 0.043), compared to those under OAD monotherapy (3.0%, 95% CI 2.7 ~ 3.4%)." (PMID 38263010, 2024). "Insulin can also activate the PKA-PhK-GP pathway, and the neuroprotective effect of insulin can be weakened by PYGB knockdown, which may be the reason for the insulin-mediated recovery in the acute and subacute phases after stroke." (PMID 38334681, 2024). "The study highlighted a 16% reduction in the risk of nonfatal stroke, emphasizing the superior efficacy of GLP-1 RAs in stroke prevention compared to traditional insulin therapy." (PMID 39262558, 2024). "The data indicates that the mean postprandial insulin level for stroke patients is 106.92 μIU/mL, while for patients without a stroke history, the mean is 128.2 μIU/mL." (PMID 39347227, 2024). "The 24-h post-ischemic intense insulin injection for AIS patients has not shown any advantage in the randomized UK Glucose Insulin in Stroke Trial (GIST-UK)." (PMID 36777640, 2023). "Third, missing data and outliers of fasting insulin or fasting free fatty acids accounted for a larger proportion of nondiabetic stroke patients." (PMID 38041145, 2023). "We did not detect differences in Iba-1+ microglia in sham-operated animals, suggesting that pre-stroke neuroinflammation was likely not involved in the detrimental effects of decreased insulin sensitivity on stroke recovery." (PMID 36835405, 2023). "In standard clinical management of stroke patients, fasting insulin levels are not routinely tested." (PMID 37633905, 2023). "In multivariate binary logistic regression analysis, the association remained significant (OR: 2.241; 95% CI: 1.439 to 3.490; P <0.001), after adjusting for age, education, SBP, history of stroke, HbA1c, HDL-C, serum tHcy, insulin or metformin usage and severe CSVD burden." (PMID 35992100, 2022). "Glycemic control achieved with the use of sulfonylureas or insulin was reported to increase the incidence of stroke in older observational studies but not in recent prospective, randomized, controlled trials." (PMID 38983558, 2022). "On the other hand, interventions with aggressive insulin therapy in acute stroke care were not beneficial." (PMID 35329949, 2022). "Early administration of basal–bolus insulin regimen in the glycemic management of hospitalized patients with stroke, rather than dependence on sliding-scale insulin, should be promoted." (PMID 34075142, 2021). "No net improvement in stroke outcome was identified, despite a significant reduction in blood glucose achieved with insulin infusion." (PMID 34054705, 2021). "Tight insulin-mediated glycemic control post-stroke in hyperglycemic patients failed to improve clinical outcomes from acute ischemic stroke in two large clinical trials, GIST-UK and SHINE." (PMID 34063817, 2021). "In conclusion, compared to basal insulin, liraglutide was found to be associated with reduced risk of a composite CVD outcome, nonfatal stroke, and all-cause mortality among high CVD risk patients with T2DM." (PMID 33446845, 2021). "Compared to nonstroke controls, stroke survivors had lower insulin-stimulated independent and fractional activity." (PMID 33375333, 2020). "The present study is the first to demonstrate reduced insulin activation of glycogen synthase in the paretic limb compared to the nonparetic limb in stroke participants." (PMID 33375333, 2020). "Other identified genes previously reported in GWAS to be associated with CVD-related traits were ELL2 (GWAS of BP, insulin and glucose), TRPS1 (GWAS of BP), PID1 (GWAS of stroke, lung function and chronic obstructive pulmonary disease) and WIPF1 (GWAS of resting heart rate)." (PMID 31999706, 2020).